LASP1NB (LASP1 neighbor)
Description:
May play a key role in the skin fibroblasts (FBs)- keratinocyte-like cells (KLCs).
Synonyms: LINC00672
Gene: Protein-coding gene on chromosome 17 (38,925,614 to 38,929,381, forward strand). Ensembl gene ENSG00000263874.
Subcellular location: Membrane
Gene Ontology:
Cellular component: membrane
Homologues: Orthologues: chimpanzee LASP1NB (100% identical), pig LASP1NB (100% identical), rabbit LASP1NB (92% identical), tropical clawed frog LASP1NB (84% identical).
Diseases named in the same sentence as LASP1NB in open-access papers:
LASP1NB is named in the same sentence as 6 diseases in open-access papers, as found by Europe PMC text mining. Sharing a sentence is not in itself a finding about the gene and the disease.
LASP1NB shares sentences with these, for which no sentence is quoted: cancer (2 papers); Alzheimer disease (1); Cognitive impairment (1); endometrial carcinoma (1); Hypertension (1); Tumor (1).